IL10 (interleukin 10)
Diseases named in the same sentence as IL10 in open-access papers (continued):
Sharing a sentence is not in itself a finding about the gene and the disease.
tumor (continued). "Beyond the immunosuppressive activity ascribed to IL-10, Mumm and colleagues demonstrated its ability to induce mechanisms involved in anti-tumor immune surveillance, in particular by favoring the expression of IFN-γ by Th1 cells and activating anti-tumor CD8+ T cells." (PMID 40236706, 2025). "Therefore, targeting highly abundant immunosuppressive cytokines such as IL-10 and TGF-β in the tumor microenvironment significantly helps to reverse immunosuppression, improving the efficacy of conventional cancer therapies, activating antitumor immunity, and controlling tumorigenesis." (PMID 40722593, 2025). "Recent studies suggest that infiltrating B cells can produce immunosuppressive cytokines such as IL-10 and TGF-β, as well as express immune checkpoint molecules like PD-L1, which contribute to the establishment of an immunosuppressive milieu that favors tumor progression." (PMID 40657381, 2025). "Tumor cells evade immune surveillance by downregulating surface antigen expression, secreting immunosuppressive factors such as transforming growth factor-β (TGF-β) and interleukin-10 (IL-10), and recruiting suppressive immune populations such as Tregs and MDSCs." (PMID 41024179, 2025). "Given the excellent efficacy of the triple treatment in inhibiting tumor progression, it is not surprising to us since TGFβ-1, IL-1β, and IL-10, and IL-30 are key mouse Th2, Th17, and Treg differentiation cytokines that have been linked to immune suppression during cancer development." (PMID 40104170, 2025). "Additionally, a tumor’s microenvironment may contain high levels of immunosuppressive cytokines such as TGF-β and IL-10, or cells like regulatory T-cells and myeloid-derived suppressor cells, which inhibit effective immune responses." (PMID 40868149, 2025). "In human tumor slice cultures (TSCs) from patients with CRLM, the addition of anti-IL-10 neutralizing antibodies significantly increased the proportion of CD8+ T cells and HLA-DR expression on macrophages, resulting in a 1.8-fold increase in T-cell-mediated tumor cell killing." (PMID 41002563, 2025). "They express the CCR2, CCR5, and CXCR2 chemokine receptors, which are then mobilized to the blood and tumor by chemokine ligands (CCL2, CCL5, CXCL1-8) and other inflammatory mediators like prostaglandin E2 (PGE2) generated by TME, VEGF, TGF-β, TNF-α, and IL-1β, IL-6, and IL-10." (PMID 40727443, 2025). "However, both lysates and EVs can also harbor immunosuppressive cytokines (e.g., TGF-β, IL-10), growth factors, and regulatory RNAs that may promote tumor progression, modulate the tumor microenvironment (TME), or suppress anti-tumor immunity." (PMID 40746549, 2025). "Additionally, the quantity and composition of TILs, particularly cytotoxic T cells (CTLs) and regulatory T cells (Tregs), are influenced by cytokines such as IL-10 and transforming growth factor beta (TGF-β), both of which contribute to immune suppression and tumor tolerance within the TME." (PMID 40881677, 2025). "Mechanistically, SPON2 enhances interleukin 10 (IL10), C-C motif chemokine ligand 2 (CCL2), and colony stimulating factor 1 (CSF1) secretion, drives M2 macrophage polarization, and activates the NF-κB/VEGF signaling axis to facilitate EMT and tumor progression." (PMID 40730813, 2025). "This suppression primarily occurs through the release of inhibitory cytokines, including TGF-β, IL-10 and IL-35, which dampen effector T-cell functions, thus reducing the activation, proliferation and cytokine production of the CAR T cells that manage to infiltrate the tumour." (PMID 40361460, 2025). "This suggests that IL-10RA could serve as an alternative target for efficiently modulating immunity through the regulation of IL-10 signalling and IDO expression, particularly relieving the immune-suppressive interaction of tumour cells/stromal cells and cytotoxic T cells with TME." (PMID 39592739, 2025).
tumor (continued). "Additionally, IL-10 fusion proteins, such as IL-10/Fc constructs, have shown potential in prolonging IL-10’s half-life, while minimizing systemic exposure, and in reinvigorating exhausted CD8+ TILs, thereby enhancing tumor-specific immune responses." (PMID 40149345, 2025). "Silibinin inhibits tumor growth through immunomodulatory activities, such as regulating immune cells (Tregs, macrophages, DCs, NK cell), inhibiting inflammatory cytokines (IFN-γ, IL-2, IL-6, IL-10, IL-12, TNF-α, and TGF-β), and modulating immune check points (PD-L1 and PD-1)." (PMID 40490812, 2025). "Furthermore, certain studies indicate that IL-10 and TGF-β may partially influence B cell infiltration in response to PTT or tumor-draining lymph nodes (TDLN), warranting further investigation." (PMID 40688079, 2025). "IL-10 could inhibit excessive activation of TLR3, and the mechanism of IL-10 involves downregulation of NF-κB pathway, which alleviated inflammatory response in tumor microenvironment." (PMID 40535567, 2025). "The galectin-3 produced by tumor cells and macrophages blocks CD8+ T cell activation signals and induces T cell apoptosis by interacting with LAG3 on the T cell surface; while FOXP3+ Tregs suppress anti-tumor immunity by secreting various inhibitory cytokines, such as TGF-β, IL-10 and IFN-γ." (PMID 41219968, 2025). "Cytokines including IFNs, interleukins (e.g., IL-2, IL-10), and granulocyte-macrophage colony-stimulating factor (GM-CSF) play pivotal roles in stimulating CD4+ and CD8+ T cell proliferation, activating dendritic cells, and enhancing tumor antigen presentation." (PMID 40849659, 2025). "Immunosuppressive cells within the tumor microenvironment disrupt T cell activation and proliferation by increasing the expression of immunosuppressive receptors such as PD-1 and CTLA-4 and by releasing immunosuppressive cytokines like IL-6, IL-10, TGFβ, and VEGF." (PMID 40625850, 2025). "Notably, MC function is dynamically regulated by tumor micro-environmental signals: IL-1, IL-4, IL-6, and TNF-α activate antitumor effects, whereas VEGF, matrix metalloproteinase, trypsin-like enzymes, and IL-10 promote malignant progression." (PMID 40960294, 2025). "TGFB additionally contributes to shaping the TME by promoting M2 macrophages and releasing interleukin-10 (IL-10), leading to an immunosuppressive cytokine milieu that contributes to a decreased immune response, ultimately hindering the effective action of CD8+ T-cells against tumor cells." (PMID 40565031, 2025). "Additionally, while tumor cells contain immune suppressive molecules such as TGF-beta, soluble HLA-G, and IL-10, intra alia, senescent cell lysates contain molecules that may actually stimulate immunity through dendritic cell maturation such as interleukin-6." (PMID 41316207, 2025). "In addition, our studies have revealed that the triple combination therapy is capable of offering improved antitumor efficacy in the TC-1 tumor mouse model, which is related to an increase in antigen-specific lymphocyte proliferation, CD8 + cytotoxicity, and IFN-γ, IL-4, and IL-10 induction." (PMID 40403026, 2025). "In cancer patients, NK cells can recognize and eliminate tumor cells by releasing cytolytic molecules perforin and granzymes, as well as modulate the adaptive anti-tumor immune response by producing chemokines and cytokines such as IFN-γ, TNF-α, IL-8, IL-10, and CCL2." (PMID 38254110, 2024). "In summary, the current study yielded new evidence that aspirin could inhibit effector T cell function via the TIGIT-BCL2-BAX signaling pathway, reducing IL-10 and TGF-β1 secretion and improving effector T cell function, ultimately contributing to the inhibition of tumor progression." (PMID 39113892, 2024).
tumor (continued). "Studies in other tumor types have identified various molecules found in the TME and expressed by tumor cells that inhibit DC activation and drive DCs toward an immunosuppressive, regulatory phenotype, including vascular endothelial growth factor (VEGF), prostaglandin E2 (PGE2), IL-10, and CSF-1." (PMID 38254796, 2024). "This suggests that the majority of potential PCNSL biomarkers, including cytokines (IL-6, IL-10) and soluble receptor proteins, may not stem directly from the tumor tissue." (PMID 39144147, 2024). "Additionally, CSCs produce immunosuppressive cytokines (like IL-4, IL-10, TGF-β, etc.), and co-inhibitory molecules (like IDO1, PD-L1, and B7-H3) that attract immunosuppressive DCs to suppress the anti-tumor immune system and activate/recruit immune suppressing Tregs." (PMID 38347575, 2024). "Surprisingly, tumorspheres derived from TMZ-treated GBM cells released higher amounts of TGF-β1 and IL-10 and were featured by a higher percentage of CD206-positive cells, supporting a macrophage polarization towards the M2 phenotype and, thus, an immunosuppressive and pro-tumor microenvironment." (PMID 38334650, 2024). "Analysis of DB7 BCBM tumor lysates using a murine bio-plex cytokine panel showed that rHSVQ treatment induced secretion of chemokines attracting Ly6G + neutrophils/PMN-MDSCs, such as CXCL1, GM-CSF, IL-6, IL-10 and MCP1, which was significantly reduced by oHSV-D11mt treatment." (PMID 38853689, 2024). "In particular, our investigation into its role in immune escape mechanisms uncovered a significant positive correlation with immune-suppressive cytokines (TGF-β, IL-10, and IL-1β) and a negative correlation with anti-tumor cytokines (IFN-γ, IL-2, and TNF-α) in metastatic lung cancer." (PMID 38951802, 2024). "M1 macrophages have anti-tumor activity and are characterized by the expression of CD68, 80, 86, and MHC-II, and M2 macrophages that promote tumor growth and are characterized by the expression of CD163, 204, 206, and secretion of immunosuppressive cytokines such as IL-10 and tumor growth factor-β." (PMID 39624236, 2024). "Tumor regrowth after hyperthermic treatment has not been extensively studied, but hyperthermia has been shown to induce immunosuppressive pathways, such as increased expression of IL-10, which dampens immune responses and promotes tumor tolerance." (PMID 39872527, 2024). "Bregs can release negative regulators such as IL-10, IL-35, and TGF-β to inhibit the immune response, suppress the activity of T cells and natural killer cells, and induce Tregs, myeloid-derived suppressor cells (MDSCs), and angiogenesis, facilitating tumor immune escape." (PMID 39840050, 2024). "M1 macrophages express Type I cytokines with an anti-tumor effect, such as tumor necrosis factor-α (TNF-α), interferon-γ (IFN-γ), IL-6; M2 macrophages express Type II cytokines, which inhibit T cell-mediated anti-tumor response, such as IL-10, IL-13, transforming growth factor-β (TGF-β)." (PMID 39735340, 2024). "In clear cell renal cell carcinoma, glutamine consumption by tumor cells results in local glutamine deprivation in the extracellular space, which activates HIF-1α to trigger TAM secretion of immunosuppressive IL-23, promoting Treg proliferation and the expression of IL-10 and TGF-β." (PMID 38185636, 2024). "Additionally, IL-10/Fc can promote the metabolic reprogramming of T cells, dependent on pyruvate and Mitochondrial Pyruvate Carrier (MPC), and induce the reactivation of terminally exhausted T cells, thereby enhancing anti-tumor immunity." (PMID 39221244, 2024). "Furthermore, high molecular weight polysaccharides extracted from Cordyceps sinensis not only enhance the immune function of mice but also induce tumor cell apoptosis through the Cytochrome-c/Caspase8/3 and IL-10/STAT3/Bcl2 pathways, thereby exerting anti-tumor effects." (PMID 38892575, 2024).
tumor (continued). "However, due to a highly immunosuppressive TME, caused by an immunosuppressive cytokine milieu/expression of the immunosuppressive molecules (for example, IL10, TGFß, PD-1L, TIM3-L, CTLA4-L, and LAC3-L), it is more likely that T effector cells within a GBM tumor lesion are suppressed." (PMID 38786032, 2024). "Additionally, IL-10 can stimulate the production of IFN-γ, which in turn increases the expression of major histocompatibility complex (MHC) molecules, enhancing the presentation of tumor antigens." (PMID 39000453, 2024). "In this study, tumor immunological profiling following bacterial depletion revealed an increase in anti-tumor immune lymphocytic cells (CD3+CD4+IFNγ+, CD3+CD8+IFNγ+, and CD3+IFNγ+), while a decrease in pro-tumorigenic IL17a (IL17a + CD3 +) and IL10(IL10 + CD4 + CD3 +)." (PMID 39044834, 2024). "IL10 promotes differentiation of Tregs, enhances tumor cell survival, proliferation, and metastasis by controlling antitumor immunity mostly through the STAT3 signaling pathway via the IL10 receptor (IL10R), whereas IL6 activates Th2 cells to promote tumor progression." (PMID 38592450, 2024). "IL-10-induced tumor rejection could not be impaired by the inhibition of T-cell trafficking from lymphoid organs, indicating its activation on tumor-resident CD8 + T cells." (PMID 38520006, 2024). "With respect to IL-10, our study showed positive associations with poor prognosis, including all-cause and BC-specific mortality, among non-metastatic cases, and in ER+PR+ and HER2- tumours." (PMID 39342063, 2024). "The feedback loop involving IL-10, CIP2A, and CREB phosphorylation may impact tumor progression." (PMID 38273373, 2024). "Accordingly, we demonstrated previously that the blockage of ILT3 during the priming of T cells by tolerogenic DCs can also block the suppressive properties of IL-10-producing CD4 and CD8 T cells 19, which could be harnessed for the development of tumour therapy." (PMID 38322117, 2024). "M1 macrophages primarily demonstrate anti-tumor effects through the secretion of cytokines like tumor necrosis factor-α (TNF-α) and interleukin-6 (IL-6), whereas M2 macrophages primarily release anti-inflammatory cytokines such as interleukin-10 (IL-10), which have promoting effects on tumor growth." (PMID 38637848, 2024). "In addition, other cytokines such as IL-10 can also regulate polarisation towards M2-type TAM through activation of STAT3 by IL-10 receptors, further accelerating TME remodelling and promoting tumour development and metastasis." (PMID 39060648, 2024). "In addition, TAMs secrete interleukin-10 (IL-10) and transforming growth factor β (TGF-β), which reduce the activity of immune cells in the organism and provide a favorable environment for tumor growth." (PMID 39175478, 2024). "The only lymphoid subset that can promote tumor progression is the regulatory CD4+ T lymphocyte subset (Treg), which directly secretes or facilitates the formation of immunosuppressive molecules (e.g., IL-10, adenosine) and modulates the APC function (e.g., via CTLA-4–CD80/86 interactions)." (PMID 38542199, 2024). "Also, the increase in IL-1β secretion along with the simultaneous decrease in TGF-β1, IL-10, and CD206 levels suggest that the COX-2 inhibition could redirect macrophages towards a pro-inflammatory, anti-tumor M1 phenotype, opposing the effects of TMZ." (PMID 38334650, 2024). "Therefore, when considering the notably low (IL‐6 and IL‐27) and high (IL‐10) level of cytokines, as well as lower number of CD163+ cells, 2‐ME may also have rendered an anti‐tumor effects such as the greater tumor necrosis." (PMID 38600057, 2024). "Thus, M2 TAMS may facilitate BLCA progression by secreting IL‐10 in the TME and promoting tumour cell migration." (PMID 38506082, 2024).
tumor (continued). "After TFF3 depletion, the expression of M2 markers (CD163, CD206, ARG-1, and IL-10) and S100A4 and S100A8 were remarkably downregulated, which confirmed our hypotheses that iCCA cells induce the M2 phenotype and pro-tumor polarization of resident macrophages by secreting TFF proteins." (PMID 39256888, 2024). "In addition, IL-10, TGF-β, and PGE2 can inhibit the maturation of dendritic cells and the expression of MHC II and B7 co-stimulating molecules on their surface, thereby influencing the recognition of the tumor." (PMID 38887597, 2024). "However, tumor cells evade immune attack by expressing inhibitory immune checkpoint receptors such as PD-1, CTLA-4, and LAG-3, as well as regulatory T cell immune suppressive molecules like TGF-β and IL-10." (PMID 38415252, 2024). "IL-10, a crucial immunoregulatory cytokine secreted by various lymphoid and myeloid cells, including Th2, CD4, CD8 T cells, NK cells, macrophages, and dendritic cells, can be produced by tumor cells themselves, acting as a cytokine synthesis inhibitory factor (CSIF) leading to immunosuppression." (PMID 39118076, 2024). "Systemic IL-10 administration, although the evidence of its efficacy on MA is limited, still emerges as a promising therapeutic strategy because it can increase CD8+ T cells cytotoxicity and invigorate exhausted CD8+ tumor infiltration lymphocytes (TILs) directly." (PMID 38279997, 2024). "Patients with B7-H2high tumor cells showed advanced TNM stage and N+ stage with decreased OS, MFS, or DFS, and this sub-cohort was featured with a trend of diminished CD4+ T cells and CD8+ cells in tumor center in situ, which positively correlated with PD-L1 and IL10." (PMID 38554152, 2024). "Cytokines produced by M2-type macrophages, such as interleukin-10 (IL-10), transforming growth factor-β (TGF-β), and anti-inflammatory cytokine α (IL-1Ra), can inhibit immune cell activation and immune-mediated killing of tumor cells, while promoting angiogenesis and tumor growth." (PMID 38910204, 2024). "While both IL-10 as an anti-inflammatory cytokine control and a carrier control showed baseline spheroid growth, both IFN-γ and TNF could, individually, promote significant tumor spheroid growth." (PMID 38226976, 2024). "APOC1 is primarily expressed in tumor cells and macrophages and shows a positive correlation with the expression of genes such as CD68, CD86, CD163, CXCL17, CXCL8, and IL-10, suggesting that APOC1 may promote tumor progression by influencing macrophage polarization." (PMID 39877420, 2024). "In addition, IL-10 can stimulate the production of IFN-γ, which in turn increases the expression of major histocompatibility complex (MHC) molecules, enhancing the presentation of tumor antigens." (PMID 38509593, 2024). "In an IL-10 transgenic mouse model, high expression of IL-10 failed to control an immunogenic lung tumor; however, administering an anti-IL-10 antibody significantly inhibited tumor growth." (PMID 39202777, 2024). "The activation of the NF-κB signaling pathway in TAM and MDSCs induces the expression of pro-inflammatory factors (IL-10) and chemokines (CCL17, CCL2), while inhibiting the expression of inflammatory cytokines (TNF α, IL-1, IL-6, etc.), leading to M2 macrophage activation and tumor evasion." (PMID 38426090, 2024). "Tregs, among them, secrete inhibitory cytokines such as interleukin (IL)‐10 and IL‐35, exerting immunosuppressive effects by influencing Antigen‐presenting cell function and inducing CD8+ cell depletion, thereby contributing to tumour development and progression." (PMID 38894548, 2024). "The intestinal tissue of IL-10 mice treated with aseptic AOM was normal without a tumor." (PMID 38415245, 2024). "In addition, IL-6 limits anti-tumor T-cell responses by promoting the differentiation of M2 macrophages or acting on dendritic cells to inhibit the expression of MHC-II, CD80/86, and IL-12 and promote IL-10 production." (PMID 38026978, 2023).